EGFR (epidermal growth factor receptor)
Diseases named in the same sentence as EGFR in open-access papers (continued):
Sharing a sentence is not in itself a finding about the gene and the disease.
renal fibrosis (continued). "In fibrotic disease induced by AKI or CKD, EGFR is frequently in a state of continuous activation in proximal tubule cells, which contributed to the progression of renal fibrosis in renal injury." (PMID 37179298, 2023). "Our previous studies have revealed that EGFR signaling induces renal fibrosis by promoting epithelial cell G2/M arrest and production of inflammatory cytokines/chemockines." (PMID 37029114, 2023). "In our study, the elevation of EGFR protein levels in the chronically infected group suggests its collaboration with various factors and pathways to induce renal fibrosis (needs further investigation)." (PMID 37626956, 2023). "SMAD4 plays a key role in regulating TGF-β–induced collagen expression and promotes SMAD3-mediated renal fibrosis while activation of EGFR serves as prognostic biomarker during chronic kidney disease." (PMID 37707956, 2023). "Inhibition of Src suppressed the activation TGF-β receptor and epidermal growth factor receptor (EGFR) and protected against renal fibrosis." (PMID 35990655, 2022). "The development of renal fibrosis is not only dependent on the activation of EGFR and PDGFRβ signaling pathways, but also on TGF-β pathways." (PMID 36139886, 2022). "Nonetheless, other studies suggest that EGFR is responsible for the renoprotective role on the renal fibrosis of I/R injury." (PMID 34545331, 2021). "Recently, AREG has been identified as an important factor for myofibroblast proliferation in many diseases, and AREG combined with EGFR amplified renal fibrosis in the proximal tubules." (PMID 33500443, 2021). "In conclusion, SAMiRNA-AREG represents a novel siRNA therapeutic for renal fibrosis by suppressing EGFR signals." (PMID 33500443, 2021). "The current study was designed to investigate the effect of erlotinib as an EGFR blocker in protection against adenine induced renal fibrosis in mice." (PMID 32661331, 2020). "Over the past decades, increasing evidence indicates that epidermal growth factor receptor (EGFR) is critically involved in the progression of CKD, exerting a pathogenic role in renal fibrosis formation (RFF)." (PMID 33469545, 2020). "Blockage of EGFR-mediated downstream signaling pathways would have therapeutic potential for inhibiting the progression of renal fibrosis." (PMID 31217524, 2019). "We observed that renal fibrosis induced by UUO was more severe in PrdxVsi mice than in PrdxVwt mice and that this effect was associated with increased EGFR/Stat3 signaling pathway activity." (PMID 31217524, 2019). "In vivo experiments suggested the activation of site-specific EGFR (Tyr1068) and subsequent activation of Stat3 as a mechanism for progressive renal fibrosis in UUO-induced PrdxVsi mice." (PMID 31217524, 2019). "Activation of the epidermal growth factor receptor (EGFR)/signal transducer and activator of transcription 3 (Stat3) signaling pathway has been reported to be associated with renal fibrosis." (PMID 31217524, 2019). "Numerous studies have demonstrated that inhibition of epidermal growth factor receptor (EGFR) alleviated renal fibrosis in various types of kidney injury models." (PMID 29207668, 2017). "Here we have utilized STZ-induced diabetic mice model and demonstrate that AG1478 markedly attenuates ER stress and promotes renal fibrosis through inhibition of EGFR/AKT activation." (PMID 28427241, 2017). "Here we provided direct evidence that suppressing EGFR prevents renal fibrosis and apoptosis in mice." (PMID 28427241, 2017). "EGFR has been confirmed to play a key role in tubular cyst formation and cell proliferation in polycystic kidney diseases, and in renal fibrosis in an experimental hypertension model." (PMID 27331812, 2016). "On the other hand, inhibition of EGFR signaling also reduced renal fibrosis by decreasing TGF-β dependent fibrogenesis." (PMID 27014908, 2016).
renal fibrosis (continued). "Mechanistic studies showed that blocking SIRT1/2 inhibits activation of epidermal growth factor receptor (EGFR) and platelet derived growth factor receptors (PDGFR), two growth factor receptors associated with renal fibrosis." (PMID 25972812, 2015). "Previous studies have shown that EGFR activation contributes to the development of renal fibrosis following a prolonged ischemic injury, renal ablation, and chronic agiotensin II infusion." (PMID 23342059, 2013). "A decrease in renal fibrosis was observed in mice with deletion of EGFR in proximal renal tubular cells after angiotensin II infusion or in Waved-2 mice that have reduced EGFR kinase activity after ureteral obstruction." (PMID 23342059, 2013). "Futhermore, suramin abolished renal ablation-induced phosphorylation of epidermal growth factor receptor and platelet derived growth factor receptor, two receptors that mediate renal fibrosis." (PMID 22558380, 2012). "Moreover, inhibition of renal fibrosis has been observed in UUO mice treated with the EGFR inhibitor gefitinib." (PMID 41318746, 2025). "Collectively, these results support the hypothesis that CL-11–induced fibroblast activation through EGFR and TGF-β signaling constitutes a central pathogenic mechanism in renal fibrosis." (PMID 40895578, 2025). "Renal fibrosis in Ang II-stimulated mice was also prevented using a new EGFR inhibitor." (PMID 39234105, 2024). "HB-EGF, another ligand for EGFR, is likely also involved in renal fibrosis." (PMID 39234105, 2024). "Remarkably, reduced renal fibrosis was accompanied by decreased EGFR phosphorylation." (PMID 39234105, 2024). "Summary of selected studies highlighting the role of EGFR signalling in renal fibrosis." (PMID 39234105, 2024). "Recent studies have reported that CTGF plays an important role in renal fibrosis by binding to EGFR on the cell surface; we speculate that CTGF may activate HSCs in an EGFR-dependent manner." (PMID 36232998, 2022). "In contrast, in UUO models, blocking DOT1L with EPZ5676 alleviates renal fibrosis by inhibiting multiple fibrosis pathways (including Smad3, EGFR, PDGFR and NF-κB pathway), up-regulating the expressions of renal protective factors such as PTEN, Klotho and Smad7,2." (PMID 35559246, 2022). "We next determined whether SAMiRNA-AREG regulated EGFR phosphorylation, which is a critical mediator of renal fibrosis and acts as a receptor of AREG." (PMID 33500443, 2021). "EGFR hyperactivation induces renal fibrosis by stimulating TGF-β signaling." (PMID 34073747, 2021). "Previous studies confirmed the upregulation of EGFR in renal fibrosis models." (PMID 33500443, 2021). "The EGFR inhibitor erlotinib can attenuate progression of kidney injury and renal fibrosis." (PMID 32661331, 2020). "Furthermore, persistent EGFR activation is critical for mediating sustained activation of the TGF‐β/Smad3 pathway in renal fibrosis." (PMID 32969198, 2020). "Through different mechanisms, therapies such as Bardoxolone, anti-miRNA-21, paricalcitol, lipid-lowering agents and epidermal growth factor receptor inhibitor, may play a certain role in mitigating renal fibrosis." (PMID 32703181, 2020). "Moreover, targeting EGFR/ERK1/2 pathway using inhibitors showed slow renal fibrosis progression in different models of fibrosis." (PMID 32661331, 2020). "Furthermore, TWEAK/Fn14 signaling induces cell proliferation and renal fibrosis through activating the EGFR pathway." (PMID 30648117, 2018).
renal fibrosis (continued). "However, further exploration illustrated that persistent EGFR activation is an essential step in renal fibrosis induced by unilateral ureteral obstruction, subtotal nephrectomy, renal hypertension, or angiotensin II/endothelin triggered renal injury." (PMID 28427241, 2017). "In the 5/6 nephrectomy renal fibrosis animal model, inhibition of EGFR and other RTKs by suramin could reduce fibrosis factor expression, and improve inflammatory cells infiltration." (PMID 27331812, 2016). "We previously demonstrated that it could specifically target EGFR and block Ang II-induced renal fibrosis via inhibiting EGFR activation." (PMID 27014908, 2016). "This suggests that EGFR is critically involved in the development of renal fibrosis." (PMID 23342059, 2013). "However, the results indicated that the Glce enzyme mutation in tubular cells did not activate the EGFR pathway but still ameliorated renal fibrosis in the UUO‐induced Glce‐/‐ mice." (PMID 40788059, 2025). "Our review paper highlights the role of epidermal growth factor receptor (EGFR) and its downstream signaling in seven different kidney pathologies: glomerulonephritis, diabetic nephropathy, hypertensive nephropathy, acute kidney injury, Chronic kidney disease, real transplant, and renal fibrosis." (PMID 39234105, 2024). "Therefore, we hypothesized that after AKI injury, EZH2 regulates PTEN transcription in TECs, thereby affecting its expression, and the subsequently phosphorylation of EGFR to regulate renal fibrosis." (PMID 37029114, 2023). "In conclusion, UPS is mainly involved in renal fibrosis through TGF-β, Wnt / β - catenin, and PINK1 / Parkin pathway and factors such as EGFR and CHK1." (PMID 40225869, 2025). "While studying the possible underlying mechanisms for this, it was found that CKD-bearing mice given Tempol (a Superoxide Dismutase-Mimetic) exhibited reduced renal fibrosis along with decreased signaling via TGF-ß/Smad3, EGFR and MAPK pathways." (PMID 39234105, 2024). "Supported by murine model evidence, it was concluded that tissue fibrosis resulting from aldosterone depends on ROS-induced EGFR/ERK activation, thus making EGFR a possible point for controlling renal fibrosis." (PMID 39234105, 2024). "EGFR activation mediates HIF-1α activation and subsequent the induction of aberrant glycolysis, which finally promoting renal fibrosis in DKD." (PMID 36874012, 2023). "The epidermal growth factor receptor (EGFR) enhances the production of the key ECM components collagen I (COL I), collagen IV (COL IV), and fibronectin (FN) in GMCs, aggravating renal fibrosis and glomerulosclerosis in DKD." (PMID 36874012, 2023). "Our recent study demonstrated that HDAC6 contribute to fibrosis by direct activation of renal interstitial fibroblast, HDAC6 involve in renal fibrosis by the activation of TGF-β1/Smad3 and EGFR signaling pathways in UUO model." (PMID 33896334, 2021). "The hematoxylin and eosin, Masson’s trichrome, and immunohistochemical staining results showed that SAMiRNA-AREG decreased renal fibrosis, AREG expression, and epidermal growth factor receptor (EGFR) phosphorylation in the UUO- and AD-induced models." (PMID 33500443, 2021). "Although the focus of this work is on TACE-dependent EGFR activation as an alternative pathway of RFF, we have also been committed to study the participation of TGF-β on renal fibrosis after treatments with losartan, erlotinib or both losartan+erlotinib." (PMID 33469545, 2020). "Our recent studies have shown that activation of EGFR mediates the development of renal fibrosis and peritoneal fibrosis and that STAT3 acts downstream of EGFR." (PMID 29179471, 2017). "Both our own studies and those from other groups have shown that activation of EGFR and PDGFR are important for the activation of renal fibroblasts and the development of renal fibrosis." (PMID 27732564, 2016).
renal fibrosis (continued). "Since RTKs (PDGFR, VEGFR, EGFR, IGFR, DDR and Axl) play a key role in renal fibrosis, understanding the mechanism by which RTKs mediate renal fibrosis is important for intervention in renal fibrosis." (PMID 27331812, 2016). "This latter finding is notable since recent studies have shown that the epidermal growth factor receptor (EGFR), is required for sustained TGF-β-dependent fibrosis in a mouse model of angiotensin II-induced renal fibrosis." (PMID 23052657, 2013). "Mechanistic studies indicate that Glce protein may bind to epidermal growth factor receptor (EGFR) to inactivate EGFR/ERK signaling and further impede TGF‐β/Smad signaling pathway and renal fibrosis in Glce‐/‐ and wild‐type mice." (PMID 40788059, 2025). "Furthermore, it was found that renal fibrosis improved along with attenuation of renal fibroblast activation by manipulating TGB-beta and EGFR signaling through blocking class I histone deacetylase." (PMID 39234105, 2024). "Inhibiting AREG, a ligand of EGFR, by AREG-targeting Self-Assembled-Micelle inhibitory RNA (SAMiRNA-AREG) in animal models of renal fibrosis resulted in decreased expression of fibrotic markers, including α-smooth muscle actin, fibronectin, α1(I) collagen, and α1(III) collagen." (PMID 39234105, 2024). "The core genes SRC, IGF1, RHOA, ESR1, EGFR and CDC42 may play a key role in the inhibition of the development and progression of renal fibrosis by diosgenin." (PMID 37179298, 2023). "EGFR as a growth factor receptor is critically involved in renal fibrogenesis, and inhibition of EGFR have been proved to account for the anti-fibrotic effect of 3-DZNeP observed in UUO-induced renal fibrosis." (PMID 37029114, 2023). "EGFR activation has been reported to participate in the activation of HIF-1α by promoting dimer PKM2 expression and enter nucleus, eventually leading to ECM accumulation and renal fibrosis in DKD." (PMID 36874012, 2023). "Moreover, EGFR overexpression plays a role in the activation of TGF-β-mediated renal fibrosis, whereas inhibition of EGFR effectively mitigates TGF-β-induced renal fibrosis." (PMID 37626956, 2023). "In fact, EGFR activation and signaling was shown to promote TGF-β–dependent renal fibrosis." (PMID 36795511, 2023). "Our results emphasize that Tenovin-1 might inhibit EGFR/PDGFR phosphorylation and attenuate renal fibrosis in HFD-induced rat models." (PMID 36139886, 2022). "Studies have indicated that EGFR is involved in the AngII and TGF-β-mediated renal fibrosis." (PMID 27331812, 2016). "Therefore, targeting EGFR and NGAL could provide a therapeutic approach to preventing renal fibrosis in long COVID." (PMID 37626956, 2023). "Studying the precise EGFR signaling cascades, it was proven that mice lacking ADAM17 in smooth muscle cells had transient protective effects from renal fibrosis." (PMID 39234105, 2024). "Accumulated data indicated that receptor tyrosine kinases (RTKs), such as EGFR, PDGFR, FGFR, and VEGFR, and non-receptor RTKs play a critical role in the pathogenesis of renal fibrosis." (PMID 38576481, 2024).
schizophrenia (60 papers, 2007 to 2025). A major psychotic disorder characterized by abnormalities in the perception or expression of reality. "Six SNPs in EGFR were significantly associated with schizophrenia, however, all fell in the range 0.01 <P < 0.05." (PMID 17598910, 2007). "Similarly, the other hub gene of cellular movement and immune cell trafficking network, EGFR, identified in Family 2 have also been associated with schizophrenia." (PMID 25943100, 2015). "An additional aspect of ERBB/EGFR signalling involves Disrupted-in-Schizophrenia-1 (DISC1), one of the most studied schizophrenia risk genes." (PMID 38674040, 2024). "and Scopolia japonica Maxim., acts as an antidopaminergic agent potentially because of the stimulation of the epidermal growth factor receptor (ErbB1 and ErbB2) phosphorylation process, alleviating the symptoms of the schizophrenia psychosis." (PMID 37627598, 2023). "As well in human post-mortem brain in schizophrenia, increased EGFR density was considered to offset the low EGF levels noted." (PMID 24552586, 2014). "This study confirms previously published associations between schizophrenia and NRG1 and ERBB4, and points to three other members of the NRG and ERBB gene families (EGFR, NRG2 and NRG3) as potential schizophrenia susceptibility genes." (PMID 17598910, 2007). "However, ERBB signalling knockout in mice also gives rise to schizophrenia phenotypes, which reinforces the view that the regulation of ERBB/EGFR signalling within OLs and myelin is complicated and complex." (PMID 38674040, 2024). "In addition to providing further evidence of NRG1 and ERBB4 associations to schizophrenia, our study is the first to suggest possible involvement of three additional genes from the NRG and ERBB gene families, i.e. NRG2, NRG3 and EGFR (ERBB1)." (PMID 17598910, 2007). "Of these pathways, schizophrenia appears to have to strongest link to the Nrg/ErbB pathway, and SNPs in several of the genes encoding Nrg (NRG1, NRG2, NRG3, and NRG6) and all of the genes encoding ErbB receptors (EGFR, ERBB2, ERBB3, and ERBB4) have been linked to schizophrenia." (PMID 30618607, 2018). "The regulation of the EGFR by quetiapine and clozapine is a novel mechanism of APD action with potential implications for the treatment of schizophrenia." (PMID 24552586, 2014). "For example, genes involved in the neuregulin 1–ErbB4 signaling pathway, including DOCK7, EGFR, PTPRZ1 and the key regulator ERBB4,45, 46, 47 were downregulated in undifferentiated and disorganized schizophrenia, while they were upregulated in paranoid schizophrenia." (PMID 28809853, 2017).